IGFBP4 (insulin like growth factor binding protein 4)
Diseases named in the same sentence as IGFBP4 in open-access papers (continued):
Sharing a sentence is not in itself a finding about the gene and the disease.
ischemia (2 papers, 2021 to 2023). A hypoperfusion of the BLOOD through an organ or tissue caused by a PATHOLOGIC CONSTRICTION or obstruction of its BLOOD VESSELS, or an absence of BLOOD CIRCULATION. "Glia-like human MSCs (ghMSCs) exhibit better efficacy and enable better protection of the neurons and the brain from ischemia than naïve human MSCs, and insulin-like growth factor binding protein-4 (IGFBP-4) played a critical role in mediating the beneficial effects of ghMSCs in an ischemic stroke." (PMID 34445248, 2021).
mammary adenocarcinoma (2 papers, 2009 to 2018). "4T1.2 mouse mammary adenocarcinoma cells transfected with empty vector, vector expressing wild-type IGFBP4 or vector expressing dBP4 were implanted in the mammary fat pad of BALB/c mice and tumour growth was assessed." (PMID 19536088, 2009). "Our engineered, PAPP-A resistant IGFBP4 (dBP4) retained IGF1 binding capacity and inhibited IGF1 activation of Akt as well as IGF1-induced migration and invasion by 4T1.2 mammary adenocarcinoma cells." (PMID 30348128, 2018). "We previously demonstrated that wild type IGFBP4 inhibited IGF1-induced proliferation of microvascular endothelial cells in vitro and that IGF1 increased VEGF production by 4T1.2 mammary adenocarcinoma cells, suggesting that dBP4 would have anti-angiogenic effects." (PMID 30348128, 2018).
Nephroblastoma (2 papers, 2013 to 2015). An embryonal neoplasm characterized by the presence of epithelial, mesenchymal, and blastema components. "Down-regulation of IGFBP-4 is associated with abnormal mitogenesis, such as in Wilms’ tumor." (PMID 24175938, 2013).
preeclampsia (2 papers, 2019 to 2022). Preeclampsia is a hypertensive disorder of pregnancy that is characterized by new-onset hypertension with proteinuria presenting after 20 weeks of gestation, and depending on mild or severe forms may initially present with severe headache, visual disturbances, and hyperreflexia. "Many insulin-like growth factor-binding proteins were also in this cluster, such as Igfbp4 and Igfbp5, which have been associated with preeclampsia and extra-villous trophoblast invasion." (PMID 30795793, 2019). "IGFBP4, a protein significantly increased in abundance in EOPE (log2FC = 4.25, FDR = 0.0003) and LOPE (log2FC = 4.91, FDR = 0.004), compared to controls, is known to have anti-angiogenic properties, adding further evidence to the central role of impaired angiogenesis in preeclampsia." (PMID 36351970, 2022). "Whilst IGFBP4 and PAPPA2 were not on the list of validated proteins, the results are convincing given the plethora of data already available related to these proteins in preeclampsia, which are also aligned to our findings." (PMID 36351970, 2022).
pulmonary fibrosis (2 papers, 2019 to 2022). Chronic progressive interstitial lung disorder characterized by the replacement of the lung tissue by connective tissue, leading to progressive dyspnea, respiratory failure, or right heart failure. "However, since we show that IGFBP‐4 levels are reduced in fibroblasts from patients with SSc‐associated pulmonary fibrosis, it is likely that an imbalance of IGFBPs can contribute to the development of fibrosis." (PMID 31482149, 2019). "Our findings demonstrate that IGFBP‐4 exerts antifibrotic effects in vitro, ex vivo, and in vivo, and its levels are reduced in primary pulmonary fibroblasts of patients with SSc‐associated pulmonary fibrosis." (PMID 31482149, 2019). "In the murine model of bleomycin-induced pulmonary fibrosis, we observed upregulation of Igf1, transient upregulation of Igfbp4 and downregulation of Igfbp6." (PMID 35741102, 2022). "The reduction in lung fibrosis was quantified using a hydroxyproline assay which showed that wild‐type and mutant IGFBP‐4 had similar antifibrotic effects and significantly reduced hydroxyproline content in mouse lungs." (PMID 31482149, 2019). "Since our data demonstrate IGFBP‐4 has antifibrotic activity, we measured IGFBP‐4 mRNA levels in primary fibroblasts from lung tissues of patients with SSc‐associated pulmonary fibrosis." (PMID 31482149, 2019). "We demonstrate that IGFBP‐4 exerts antifibrotic effects as demonstrated in vitro using primary human pulmonary fibroblasts, in vivo using the murine bleomycin model of pulmonary fibrosis, and ex vivo using human skin and lung tissues in organ culture." (PMID 31482149, 2019). "Having demonstrated that IGFBP‐4 exerts antifibrotic effects in vitro and ex vivo, we tested its ability to ameliorate fibrosis in vivo in a murine bleomycin‐induced pulmonary fibrosis model." (PMID 31482149, 2019). "Histologic assessment of H&E‐stained sections shows that both wild‐type and mutant IGFBP‐4 reduced lung fibrosis." (PMID 31482149, 2019). "Based on our findings, we propose that decreased levels of IGFBP‐4 in SSc fibroblasts may be responsible for increased CXCR4 in lung fibrosis and ultimately the promotion of CXCR4‐dependent chemotaxis of circulating monocytes and inflammatory cells, contributing to pulmonary fibrosis." (PMID 31482149, 2019). "We sought to examine the effects of another member of the family, IGFBP‐4, on ECM production and fibrosis using cell‐based, ex vivo organ culture and in vivo mouse lung fibrosis models." (PMID 31482149, 2019).
rickets (2 papers, 2010 to 2019). Bone softening and weakening usually caused by deficiency or impaired metabolism of vitamin D. Deficiency of calcium, magnesium, or phosphorus may also cause rickets. "The results of this study demonstrate that circulating IGFBP-4 levels are not influenced by secondary hyperparathyroidism in vitamin D deficiency rickets since IGFBP-4 levels did not change after normalization of PTH with vitamin D treatment." (PMID 21274331, 2010). "Thus, to investigate the role of PTH in the regulation of IGFBP-4 levels, we prospectively measured serum IGF-I, IGFBP-3, IGFBP-4 and PTH concentrations in infants with nutritional rickets before and after treatment." (PMID 21274331, 2010). "Serum IGF-I and IGFBP-3 levels both increased after treatment for rickets, while serum IGFBP-4 levels did not change significantly (18.8±8.0 vs. 21.5±4.8 ng/ml)." (PMID 21274331, 2010).
squamous carcinoma (2 papers, 2017 to 2025). "On the contrary, IGFBP-4 was identified as a potent inhibitor of angiogenesis in models of squamous cell carcinoma where IGFBP-4 neutralization improved angiogenesis and tumor outgrowth." (PMID 41226289, 2025). "Additionally, we next conducted qRT-PCR analysis to examined lnc-IGFBP4–1 expression in LC cell lines, involving both adenocarcinoma and squamous carcinoma subtypes." (PMID 28946875, 2017).
Stroke (2 papers, 2010 to 2013). Sudden impairment of blood flow to a part of the brain due to occlusion or rupture of an artery to the brain. "Here, our validation exercises confirm a positive association of plasma IGFBP2 and IGFBP4 with stroke risk among postmenopausal women." (PMID 24373343, 2013). "B2M, THBS1, and CFD were confirmed (P <0.05) as novel CHD risk markers, and B2M, IGFBP2, and IGFBP4 were confirmed as novel stroke disease risk markers, while the assay for HPX proved to be unreliable." (PMID 24373343, 2013). "This work has also led to the identification of plasma B2M, IGFBP2, and especially IGFBP4 as novel risk markers for stroke risk among postmenopausal women." (PMID 24373343, 2013). "The CFD associations with CHD were primarily evident in the active treatment groups in both trials; whereas the IGFBP4 association with stroke was most evident in the placebo groups for both trials." (PMID 24373343, 2013). "We previously reported positive associations of baseline B2M with CHD risk and baseline IGFBP4 with stroke risk during the first year from randomization in the WHI HT trials." (PMID 24373343, 2013). "The discovery and replication studies presented here also show IGFBP4 to be a risk marker for stroke in postmenopausal women, which appears to be a novel finding." (PMID 20667078, 2010). "However, there was limited evidence of important mediation of HT effects on stroke by either IGFBP4 or IGFBP2, and only a weak suggestion of a positive association between IGFBP4 change from baseline to year 1 and stroke risk." (PMID 24373343, 2013). "Also, it is interesting that four of the eleven top-ranked proteins for association with stroke risk are members of the IGF signaling pathway (IGFBP4, IGF2, IGFBP6, IGFBP2)." (PMID 20667078, 2010). "The associations of B2M with CHD (P < 0.001) and IGFBP4 with stroke (P = 0.005) were confirmed using ELISA in replication studies, and changes in these proteins following the initiation of hormone therapy use were shown to have potential to help explain hormone therapy effects on those diseases." (PMID 20667078, 2010). "Plasma THBS1 and CFD are confirmed as CHD risk markers, and plasma IGFBP4 and IGFBP2 are confirmed as stroke risk markers." (PMID 24373343, 2013). "The strongest associations in these analyses are for B2M and CHD and for IGFBP4 and stroke, while an inverse association of CHD risk with THBS1 and a positive association of stroke risk with IGFBP2 are also observed." (PMID 24373343, 2013). "For B2M, combined trial case-control differences at 1 year were evident for both CHD and stroke; and for IGFBP4, were evident for stroke." (PMID 24373343, 2013). "Combined trial comparisons show CHD case-control differences (P <0.05) for B2M and CFD, and stroke case-control differences for B2M and IGFBP4." (PMID 24373343, 2013). "These analyses also imply positive associations of stroke risk with IGFBP2, IGFBP4, and B2M." (PMID 24373343, 2013). "In-depth proteomic discovery analysis of prediagnostic plasma samples identified B2M and IGFBP4 as risk markers for CHD and stroke respectively, and provided a number of candidate markers of disease risk and candidate mediators of hormone therapy effects on CHD and stroke." (PMID 20667078, 2010). "We have identified B2M and IGFBP4 as novel risk markers for CHD and stroke, respectively." (PMID 20667078, 2010). "IGFBP4 is of specific interest for stroke for these same reasons." (PMID 20667078, 2010). "For stroke, positive correlations of B2M with each of IGFBP2, IGFBP4, and IGFBP6 were also evident at baseline and year 1 in both treatment groups, and both trials." (PMID 24373343, 2013). "To more directly assess the role of B2M and IGFBP4 in mediating hormone therapy effects on CHD and stroke, respectively, we are currently carrying out ELISA analyses of baseline and 1-year plasma samples in the WHI hormone therapy trials." (PMID 20667078, 2010).
Stroke (continued). "Corresponding numbers for stroke were 47 proteins with nominal P < 0.05, three of which, apolipoprotein A-II precursor (APOA2), peptidyl-prolyl isomerase A (PPIA), and insulin-like growth factor binding protein 4 (IGFBP4), have a false discovery rate < 0.05." (PMID 20667078, 2010).
type 2 diabetes (2 papers, 2015 to 2017). "We selected 14 disallowed genes for analysis based on their identification in 2 independent studies (C1qbp, Cd302, Cxcl12, Igfbp4, Ldha, Lmo4, Maf, Oat, Pdgfra, Slc16a1, and Smad3) and/or other criteria including up-regulation in type 2 diabetes (Acot7, Ldha, and Pdgfra)." (PMID 26038943, 2015).
Arthritis (1 paper, 2020). Inflammation of a joint. "IGFBP4 (144 ng), with IGFBP6 (85 ng) and 3 (10 ng), was shown to balance the IGF-dependent induction of CD4+FOXP3+ Tregs given by MSC-conditioned medium in arthritis." (PMID 32345351, 2020).
autoimmune disease (1 paper, 2022). A disorder resulting from loss of function or tissue destruction of an organ or multiple organs, arising from humoral or cellular immune responses of the individual to their own tissue constituents. "IGFBP-4, which is typically expressed in the kidneys, has been suggested as a marker for autoimmune diseases, including chronic lupus nephritis." (PMID 35148702, 2022).
cholangiocarcinoma (1 paper, 2024). A carcinoma that arises from the intrahepatic biliary tree (intrahepatic cholangiocarcinoma) or from the junction, or adjacent to the junction, of the right and left hepatic ducts (hilar cholangiocarcinoma). "To verify whether the inhibitory effects of miR-122-5p on the invasion and metastasis of cholangiocarcinoma occurs through the regulation of IGFBP4, we performed rescue assays." (PMID 37349627, 2024).
coronary atherosclerosis (1 paper, 2012). Atherosclerosis of the coronary vasculature. "Based on this observation, it is possible that the biological consequence of CRP- and TNF-α-induced PAPP-A expression in human PBMCs was enhanced IGF-I bioactivity mediated by PAPP-A proteolysis of IGFBP-4, thus contributing to the progression of both coronary atherosclerosis and restenosis." (PMID 22997483, 2012).
dialysis (1 paper, 2018). "Furthermore, peritoneal tissue from peritoneal dialysis patients showed less prominent immunostaining than control tissue for IGFBP4 and BMP4 on the peritoneal surface." (PMID 29774544, 2018).
endometrioid ovarian cancer (1 paper, 2020). "In addition, the IGFBP4 protein expression was upregulated in SOC, and the IGFBP6 protein expression was upregulated in both of SOC and endometrioid ovarian cancer (EOC) tissues." (PMID 33282953, 2020).
endophthalmitis (1 paper, 2025). An infectious process affecting the internal structures of the eye. "In the HVIP1 vitreous, there were a number of significant correlations identified: CRP/Myoglobin, IGFBP-4/SAA, IGFBP-4/VCAM-1, and VCAM-1/SAA in the endophthalmitis group; MPO/NGAL, CRP/SAA, and Cystatin C/Myoglobin in controls; and NGAL/MMP-9 in both groups." (PMID 40563988, 2025).
esophageal cancer (1 paper, 2020). A primary or metastatic malignant neoplasm involving the esophagus. "Increased expression of IGF1R, IGFBP3, IGFBP4, IGFBP7, and IGFBP8 was reported in human esophageal cancer, while the expression of IGFBP2 and IGFBP6 was reduced." (PMID 32041673, 2020).
glomerular diseases (1 paper, 2016). "Compared to the healthy controls or other glomerular disease controls, serum IGFBP-4 levels were significantly higher in the patients with LN." (PMID 27019456, 2016). "Furthermore, serum IGFBP-4 levels appear to be able to discriminate LN patients from healthy volunteers and from patients with other glomerular diseases." (PMID 27019456, 2016).
hyperparathyroidism (1 paper, 2010). Hyperfunction of the parathyroid glands resulting in the overproduction of parathyroid hormone. "To further investigate the role of PTH in regulation of IGFBP-4, we wanted to measure serum IGFBP-4 levels in situations, where hyperparathyroidism is more prominent and reversible." (PMID 21274331, 2010).
intrahepatic cholangiocarcinoma (1 paper, 2024). A carcinoma that arises from the intrahepatic bile duct epithelium in any site of the intrahepatic biliary tree. "Our study revealed a novel mechanism of miR-122-5p by which it can directly bind to the promotor region of IGFBP4 activating its transcription and attenuate the metastasis of intrahepatic cholangiocarcinoma." (PMID 37349627, 2024).
lung adenocarcinoma (1 paper, 2021). A carcinoma that arises from the lung and is characterized by the presence of malignant glandular epithelial cells. "A study of lung adenocarcinoma cells has suggested that epigenetically suppressed IGFBP-4 positively affects tumour growth by reducing IGF inhibition." (PMID 34177367, 2021).
medulloblastoma (1 paper, 2013). A malignant, invasive embryonal neoplasm arising from the cerebellum. "Protein levels of IGFBP-4 and IGFBP-6 were also noted to be significantly elevated in the CSF of medulloblastoma patients (p = 0.011 and p = 0.010, respectively)." (PMID 24400253, 2013).
metastatic melanoma (1 paper, 2008). A melanoma that has spread from its primary site to another anatomic site. "First, we demonstrate that tissue expression of IGFBP-4 decreases in the progression from primary to metastatic melanoma." (PMID 19025658, 2008). "The median IGFBP-4 expression in metastatic melanoma specimens was 10%, significantly lower than IGFBP-4 expression in primary tumors (p = 0.01, Wilcoxon rank-sum test)." (PMID 19025658, 2008). "Decreased IGFBP-4 tumor expression might be a step in the progression from primary to metastatic melanoma." (PMID 19025658, 2008). "We report for the first time data which demonstrate the up-regulation of IGFBP-4 expression in primary versus metastatic melanoma specimens, and these data suggest that IGFBP-4 may function as a tumor suppressor." (PMID 19025658, 2008).
myopia (1 paper, 2023). "Further analysis using an insulin microarray resulted that the levels of insulin and those related factors including IGF2, IGF-2R, IGF binding protein 1 (IGFBP-1), IGFBP-2, IGFBP-3, IGFBP-4 and IGFBP-6 were markedly increased in patients with pathogenic myopia as compared with the controls." (PMID 38203671, 2023).
non-small cell lung carcinoma (1 paper, 2014). A group of at least three distinct histological types of lung cancer, including non-small cell squamous cell carcinoma, adenocarcinoma, and large cell carcinoma. "Specific and IGF-dependent proteolytic cleavage of IGFBP-4 has previously been documented in conditioned media from non-small cell lung cancer cell lines, although the identity of the responsible proteinase was unknown then." (PMID 24572990, 2014).
osteoarthritis (1 paper, 2024). A noninflammatory degenerative joint disease occurring chiefly in older persons, characterized by degeneration of the articular cartilage, hypertrophy of bone at the margins and changes in the synovial membrane. "Eight markers were found to be associated with an increased risk of osteoarthritis, including serum testosterone, serum dihydrotestosterone, sex hormone-binding globulin, glycosylated hemoglobin (HbA1c), insulin-like growth factor-binding protein 4, lipocalin, leptin, and resistin." (PMID 39172202, 2024).
ovarian tumors (1 paper, 2015). "In conclusion, human ovarian tumors express PAPP-A, IGFBP-4 and IGFs and these proteins are also present in ascites." (PMID 26336825, 2015).
periodontitis (1 paper, 2022). An acute or chronic inflammatory process that affects the tissues that surround and support the teeth. "Unlike IGFBP4, OPG is up-regulated in the presence of P. gingivalis in P-GMSCs, suggesting that GMSCs chronically stimulated with P. gingivalis during periodontitis may be a target for promoting blastogenesis and bone repair." (PMID 35408871, 2022).
Peritoneal Fibrosis (1 paper, 2018). Disorder characterized by a wide range of structural changes in PERITONEUM, resulting from fibrogenic or inflammatory processes. "Another approach, however, based on the findings from the current study, would be to focus on introducing BMP4 and IGFBP4 to prevent MMT and peritoneal fibrosis." (PMID 29774544, 2018).
pulmonary disease (1 paper, 2022). "IGFBP-4 levels were correlated with pulmonary disease activity and several lung function indicators." (PMID 35356065, 2022).
renal fibrosis (1 paper, 2016). A final common manifestation of a wide variety of chronic kidney diseases characterized by glomerulosclerosis and tubulointerstitial fibrosis. "As IGFBP-4 is an important regulator of the IGF system, it will be very interesting to determine whether IGFBP-4 and IGFs play a role in the pathogenesis of renal fibrosis." (PMID 27019456, 2016).
secondary hyperparathyroidism (1 paper, 2010). Overproduction of parathyroid hormone in response to influence external to the parathyroid glands. "They suggested that secondary hyperparathyroidism, which occurs as a consequence of age, could induce the inhibition of osteoblast proliferation by production of IGFBP-4 in the locale of bone-remodeling sites." (PMID 21274331, 2010).